CD44 (CD44 molecule (IN blood group))
Diseases named in the same sentence as CD44 in open-access papers (continued):
Sharing a sentence is not in itself a finding about the gene and the disease.
tumor (continued). "Lewis X, the markers of stemness (CD44 expression, ALDH, Sox2), and tumor-sphere formation, chemoresistance to 5-FU treatment, and proliferation of tumor in vivo were increased in FUT9-expressing murine colon adenocarcinoma cells compared with control cells." (PMID 34948129, 2021). "Since then, reports have identified CD44+ cells to be enriched for CSC-like properties, CD26+ cells capable of initiating tumor formation and facilitating EMT, and LGR5+ normal intestinal SCs serving as the tumor cells of origin." (PMID 33763422, 2021). "We found that a subset of CD44+ BCSCs with high expression levels of PKD-1 and CD36 were localized within or near blood vessels and tumor nests." (PMID 34168243, 2021). "BD also demonstrated therapeutic potential by interfering with the tumor cell–TME interactions by reducing the amyloid beta precursor protein and CD44 expression." (PMID 34685653, 2021). "The function of CD44+/CD24−/low cells in BC was demonstrated in samples of nine patients, where they were showed to induce tumor development in NOD/SCID mice, in contrast to the use of cells with a different immunophenotype." (PMID 33802575, 2021). "Using immunofluorescence (IF) staining of tumor sections from EPN and AEP patients, we confirmed the presence of CCL2+ TAMs and CD44+ TAMs as subgroups and observed higher proportions of these two TAM subsets in AEP." (PMID 34824203, 2021). "GSC‐HI cells expressed the highest level of CD44 and had the highest invasion and migration of the tumor cells, whereas GDC40 cells expressed the lowest level of CD44 and showed the lowest activities of invasion and migration." (PMID 33543833, 2021). "Tumor-infiltrating CD8 + T cells showed higher proliferation (Ki67 +) and enhanced activation (CD44 +) in mRBC-240 treated mice compared with mRBC-CTRL (p = 0.044 and p = 0.034, respectively)." (PMID 34244816, 2021). "CD44 and VEGF expression in the tumor core and periphery of 22 GBMs was examined, and the relationship between expression of these molecules and progression‐free time on Bev therapy was analyzed." (PMID 33543833, 2021). "Immunohistochemical analysis of tumor tissues from the in vivo models confirmed that TS120-T peptide treatment reduced the cellular levels of TSPYL5, thereby resulting in decreased CD44 and increased PTEN levels." (PMID 34163000, 2021). "CD8α ALN-1 strongly shifted the phenotype of the infused T cells towards an effector phenotype, characterized by a CD44+CD62L- profile and T-bet expression, in the TDLN and the tumor." (PMID 34772757, 2021). "This indicated that vesicles composed of HA-VE/PBAEss copolymers had accumulated in the tumor, which would contribute to the prolonged circulation, EPR effect, and tumor-targeting mediated by HA and CD44 interaction." (PMID 34162396, 2021). "Both colony formation and tumor sphere formation corresponded to the ALDH1+ and CD44+ population levels with GA0518 the highest." (PMID 34162421, 2021). "Further studies showed that in the internal environment of SD, CTLA-4 promoted tumor invasion and metastasis by regulating the PTEN/CD44 pathway." (PMID 34744733, 2021). "In the present study, GBMs with higher CD44 and lower VEGF expression in the tumor periphery showed much more resistance to Bev therapy than GBMs with lower CD44 and higher VEGF expression in the tumor periphery." (PMID 33543833, 2021). "The higher proportion of CD44+/CD24− cells in BCSC4 would suggest a higher BCSC potential, but BCSC4 showed less colony and sphere formation and substantially slower tumor growth compared to BCSC3." (PMID 33670400, 2021). "Through activating receptors such as integrins and CD44, OPN can foster survival, proliferation, motility, and invasion of tumor cells, and can stimulate angiogenesis." (PMID 34611309, 2021).
tumor (continued). "Given the increased expression of XBP1, CXCR4, and CD44 during ERS/UPR activation under hypoxic condition in DLBCLs, we further investigated possible contribution of this pathway to the tumor APVT growth pattern." (PMID 34093792, 2021). "Accumulating research indicates that cancer cells expressing the surface marker phenotype CD44+/CD133+ have stem cell-like traits and possess self-renewal and tumor-initiating capacity." (PMID 32005118, 2020). "Isolation of the CD44+ population from human HCC cells and incubation with TAM induced expansion of this cell population and tumor sphere formation." (PMID 32466488, 2020). "FKBPL-based therapy can (i) dually target angiogenesis and CSCs, (ii) target the CD44/STAT3 pathway in tumours and (iii) is effective in highly vascularised HGSOC tumours with low levels of IL-6." (PMID 31772325, 2020). "There was a quantitative difference though: in SW480 xenografts, only a tumor cell fraction of 17±9% established CD133-positivity, whereas 64±13% still expressed CD44." (PMID 32685007, 2020). "Future studies on targeted CSC therapy can focus more on K19, CD90, CD44, Toll-like receptors 4 (TLR4), SRY-related HMG-box gene 12 (SOX12), and aldehyde dehydrogenase (ALDH) to inhibit tumor metastasis." (PMID 32210805, 2020). "Compared with other GAGs forming PG, the basic structure of HA is a large polysaccharide that can interact with various membrane receptors and cell surface glycoproteins, including CD44, HMMR, EMMPRIN, and LYVE-1, to control tumor cell fate." (PMID 32825245, 2020). "Since BCSCs were first identified in 2003 based on CD44 and CD24 expression, different biomarkers for BCSCs have been identified in BC patient tumor samples, animal models, and cell lines, indicating the existence of a variety of BCSC subgroups." (PMID 33327542, 2020). "Mice harboring RT-R-MDA-MB-231 cell xenografts showed enhanced tumor growth and higher expression of the CSC markers, CD44, Notch-4, and Oct3/4." (PMID 33126606, 2020). "Various EMT inducing proteins such as MMP-2, vimentin, snail, slug, N-cadherin and CD44 were analyzed in C4-2 and WT-SPOP tumor lysate." (PMID 33158056, 2020). "Collectively, these observations support a prominent role for CD44 and STAT3 crosstalk in mediating tumor and TAM interactions within the ovarian TME." (PMID 33335857, 2020). "The uniform-sized spherical nanoparticles demonstrated a high affinity and specific binding to CD44-enriched B16F10 cells, as well as tumor internalization in a mouse lung-tumor model, which significantly limited tumor growth and metastasis." (PMID 33291312, 2020). "Ectopic overexpression of miR-200c in the CD117+/CD44+ cells inhibited EMT and induced tumor suppression by directly repressing ZEB1 and Vimentin, which resulted in a subsequent upregulation of the E-cadherin expression." (PMID 32850313, 2020). "The combination therapy of CD44-targeted NIR-PIT and CTLA4 blockade showed only similar level of T cell infiltration in tumor beds compared with CTLA4 blockade alone one week after therapy." (PMID 32937841, 2020). "In tumor xenograph studies, SNC also reduced expression of Wnt target genes including CD44, Sox2 and LGR5." (PMID 33347461, 2020). "We investigated the effect of combining tumor-targeted NIR-PIT against the cell-surface antigen, CD44, which is known as a cancer stem cell marker, with a systemic CTLA4 immune checkpoint inhibitor in three syngeneic tumor models (MC38-luc, LL/2, and MOC1)." (PMID 32937841, 2020). "Collectively, these results show that CD44 and STAT3 can regulate each other’s expression and cooperate across different tumor types to drive cancer invasion, metastasis, disease recurrence, and chemoresistance." (PMID 33335857, 2020). "CD44 and STAT3 cooperate at multiple levels in both malignant and the normal cells in the tumor microenvironment, leading to cancer progression and resistance to therapies." (PMID 33335857, 2020).
tumor (continued). "The inhibition of stem cell characteristics by KYA1797K was also indicated by growth suppression of tumor organoids, with reductions in the cancer stem cell (CSC) markers CD44 and aldehyde dehydrogenase 1 (ALDH1) A320,21." (PMID 32457491, 2020). "HA promotes mobility and drug resistance of tumor cells through the expression of hyaluronan-mediated motility (RHAMM) and interaction with CD44." (PMID 32308769, 2020). "Stemness in BC is mainly identified by increased presence of CD44+/CD24− cells or CD44+/CD24− low cells, and ALDH+ cells; by the expression of stemness genes and/or by the ability of the tumor cells to form mammospheres (tumor spheres)." (PMID 33585241, 2020). "CD44, CD133, CD24, and ALDH activity are frequently used for the detection and isolation of CSCs from tumor tissues and many cancer cell lines." (PMID 32814771, 2020). "We measured CSC populations by flow cytometric analysis (CD44+/CD133+) and by tumor spheroid growth." (PMID 32911743, 2020). "Correspondingly, we observed increased tumor infiltrated CD4+CD44+ and CD8+CD44+ T cells upon Bcl6 deletion in Treg cells." (PMID 32477338, 2020). "In view of the increased ALDH and CD44 expression in ascites-derived tumour cells, FACS was employed to isolate ALDH+CD44+ and ALDH−CD44− subsets of SKOV3 and OVCAR3 cell groups." (PMID 32390009, 2020). "In contrast, 1 × 103 CD133+CD44+ cells from the first-generation xenografts maintained their tumorigenic potential and were able to transfer the tumor into secondary mice, confirming the data obtained with CD133+CD44+ cells directly isolated from cell lines." (PMID 32729895, 2020). "In the NOD/SCID mice model of breast cancer, CD44+CD24−/low cells exist in a very small population but possess the ability to aid tumor growth and even form complete original tumor tissue." (PMID 32121074, 2020). "Pretreatment BCSC markers (CD44 and CD24) were assessed by immunohistochemistry on formalin-fixed paraffin-embedded tumor tissues from a primary or metastatic site." (PMID 32684928, 2020). "Results revealed that the expression of stem cell markers identified as CD44, NANOG, OCT3/4, and CD24 in tumor cells was strongly attenuated by SR59230A treatment." (PMID 32093135, 2020). "CD44 gene is a common marker of CSC and shown to express in many tumors to play a significant role in cell growth, survival, tumor proliferation, metastasis, resistance." (PMID 33381460, 2020). "In contrast, virtually all CDX tumor cells expressed neuron-specific enolase (NSE), chromogranin A, Ki67, and CD44 evidencing emergence of an AR-null, neuroendocrine-positive phenotype." (PMID 32313004, 2020). "Yet, other long-time discovered molecules at the interface between tumor cell and ECM as CD44, DDR, LAMR, FAK, and SFK, are emerging as alternative therapeutic targets in clinical trials." (PMID 32793493, 2020). "Our data showed the reduction of CD44+/CD24− subpopulation, mammosphere formation, colony formation and tumor formation." (PMID 32503228, 2020). "We showed that high levels of CD44, a well-known GSC marker, were prevalent in PZ, in line with the notion that GSCs are enriched within a hypoxic tumor niche where the oxidative stress is elevated." (PMID 32823815, 2020). "They showed a significant co-upregulation of CD44 and basal-type KRT14, which is correlated with tumor recurrence and short survival rates." (PMID 31963556, 2020). "Taken together, the results of the present research highlight a strong similarity between ALDHhigh and CD44+/EPCAM+ cells, as suggested by cytofluorimetric analyses, tumor sphere-forming assays, and RT-PCR experiments." (PMID 32391123, 2020). "For instance, a previous study demonstrated that the combination of CD44-targeted NIR-PIT and either immune checkpoint blockade or Treg-targeted NIR-PIT showed inconsistent therapeutic efficacy among these three tumor models." (PMID 32927646, 2020).
tumor (continued). "The CD44-targeted NIR-PIT group and combination group showed significantly greater tumor reduction compared to the CTLA4 mAb group." (PMID 32937841, 2020). "This was evidenced by a CCL2-promoted formation of primary and secondary tumor spheroids that contained more self-renewing CSCs, and by the fact that stimulation of breast tumor cells with CCL5 increased the CD44+/CD24− sub-population." (PMID 32582148, 2020). "With the combination of IL-15 and CD44-targeted NIR-PIT, the number of Gzmb-positive CD8 T cells in the tumor tissue significantly increased at day 7 after the therapy." (PMID 32927646, 2020). "Expressions of CD90, EpCAM, CD133, CD24, SOX9, CD44, CK19, and CD47 were positively related to immune infiltration level in HCC, negatively related to tumor purity." (PMID 32184801, 2020). "At the molecular level, both CD44 and STAT3 have been reported to support tumor angiogenesis in several tumor models." (PMID 33335857, 2020). "Both CD44-targeted NIR-PIT and combination groups showed significantly smaller tumor volume than CTLA4 mAb group at 2, 5, 7, 10, 12, and 14 days after NIR-PIT (p < 0.05, Tukey–Kramer test)." (PMID 32937841, 2020). "EV isolated from the sera of MM patients were highly enriched in tumor-related CD markers CD38, CD138, and CD44." (PMID 33316884, 2020). "We have previously demonstrated that the small specific molecule CBP/β-catenin antagonist ICG-001 can inhibit the migration and growth of CSC-enriched NPC tumor spheres via the miRNA-145/SOX2 (SRY-Box Transcription Factor 2) axis and miR-150/CD44 axis." (PMID 32752071, 2020). "CR1 promotes the tumor growth of colorectal CSC/progenitors in vivo and in vitro, by activating the Glypican/Src/AKT pathway and inducing CD44 expression." (PMID 32456226, 2020). "Tumours were collected, minced and dissociated for secondary implantation onto another batch of nude mice to assess the self-renewal capacity of ALDH+CD44+ cells." (PMID 32390009, 2020). "Localization of CD44-ICD and RUNX2 in the nuclei of adenocarcinoma further highlights the potential role of these proteins in transcriptional regulation and tumor progression." (PMID 33062960, 2020). "In parallel, CXCL1 arriving from TAMs was found to promote the CD44+/CD24− sub-population and formation of tumor spheroids in human TNBC cells." (PMID 32582148, 2020). "Their strategy takes advantage of the presence of markers (CD44, CD133) highly expressed on tumor cell membrane." (PMID 32731612, 2020). "For CD44-positive BEL 7402 cells, the results showed a significant reduction in tumor volume compared to the sorafenib in the combination treatment groups." (PMID 31992334, 2020). "Then, we dissociated PTC-CSCs from tumor spheres derived from TPC1 and BCPAP cells, and recognized these PTC-CSCs with higher CD133+CD44+ and higher expression of stemness specific proteins than parental cells." (PMID 32917852, 2020). "The PCSCs isolated from AR-negative DU145 cells show higher expression of CD44, CD24, integrin α2β1, cellular reprogramming factor SOX2, and exhibit tumor-initiating potential and self-renewal ability." (PMID 32754615, 2020). "Below, we discuss potential roles for CD44 and STAT3 in different aspects of metabolism switch in cancer cells that support tumor progression." (PMID 33335857, 2020). "Breast CSCs express characteristic markers such as CD44+/CD24−/low, CD133 and ALDH1 and are involved in tumor initiation, formation, and recurrence." (PMID 33102470, 2020). "To assess the effects of DCA on tumour formation in vivo, we inoculated control or DCA-pre-treated ALDH+CD44+ SKOV3 cells into the flanks of nude mice and recorded tumour formation times, sizes and weights." (PMID 32390009, 2020). "Two significant CSC characteristics (tumour initiation and self-renewal) of ALDH+CD44+ cells were investigated using in vivo tumorigenesis and limiting dilution assays." (PMID 32390009, 2020).
tumor (continued). "The mRNA levels of CSCs markers (CD44 and CD24) and EMT markers (E-cadherin, β-catenin, vimentin, and N-cadherin) in tumor tissues were analyzed with qRT-PCR." (PMID 33282946, 2020). "C-B and C-I downregulated the expression of DCLK1, CD44 and LGR5 in HCT116 tumor samples relative to the vehicle control." (PMID 31992775, 2020). "Again, all dormant tumor cells that grew in culture from the lungs showed comparable levels of expression of neu or EpCAM and were predominated by the CD24+CD44+ fraction." (PMID 33115528, 2020). "CD44 has been reported to serve as a platform for signaling transduction, including MAPK/PI3K and β-catenin signaling, to promote tumor progression and metastases." (PMID 31898491, 2020). "In vitro data reported that anti-CD44 antibody-mediated liposomal NPs loaded with doxorubicin efficiently targeted the HCC cells compared to normal liver cells and significantly reduced tumor growth." (PMID 32184825, 2020). "Identification of cancer stem cells (CSCs) can be achieved by evaluation for surface markers, such as CD44 and CD133, via immunostaining, or by performing sphere formation assays and in vivo tumour initiation assays." (PMID 33158116, 2020). "CD44, as a well-known constituent of CSC niche, is among the chief potential rewarding anti-cancer targets for tumor management." (PMID 33303029, 2020). "Binding of HA to its primary receptor CD44 induces TGF-β receptor (TGFBR) activation, disturbances in cell adhesion to extracellular matrix components, inflammation, development, tumor growth, and metastasis." (PMID 33072083, 2020). "All SCLC CTCs are CD24-positive but lack expression of CD44 and ABCG2 in contrast to the SCLC tumor lines which show a phenotype more similar to that of CSCs." (PMID 31446534, 2020). "Marked overexpression of DUSP4, CD44, MUM1/IRF4, BCL-2, CD146/MUC18, IGF1R, and AKT3 was observed in the tumour cells in all mUM, compared to the background hepatocytes." (PMID 33008022, 2020). "With its known signaling mechanisms, CD44 has dual functions in the TME that can both support and attenuate tumor progression, depending on the differential expression, processing and fragmentation of its ligand, hyaluronic acid, in the course of tumor growth." (PMID 33379400, 2020). "Blotting the tumor lysates for MES markers (fibronectin, CD44, and CTGF) revealed that LN229TAZ(4SA) tumors express these proteins at higher levels, suggesting a MES transformation in vivo." (PMID 33110073, 2020). "In D-17 we highlighted the basal expression of both CD44 and CXCR4; the first is a trans-membrane protein involved in the tumor microenvironment that interacts with various components of the extracellular matrix, cytokines and growth factors." (PMID 33126659, 2020). "On the other hand, our results showed that GANT61 treatment significantly decreased levels of CD44 in HCC PDOs and cotreatment of sorafenib and that GANT61 inhibited the tumor growth both in vitro and in vivo." (PMID 31992334, 2020). "CD44 and CD133 are multifunctional cell surface antigens that have a role in tumor proliferation, migration, invasion, and angiogenesis in several aspects of cancer cell phenotypes and have been extensively studied as single and combined CSC markers." (PMID 32560537, 2020). "In this study, we also found that high levels of soluble CD44, CD44v6, CD44v8-10 and EpCAM were correlated with elevated levels of CA19-9, suggesting that their expression is involved in tumor progression." (PMID 32039729, 2020). "CD44 was reported to take part in GBM playing a role in cell invasion and proliferation, tumor growth and inhibition of apoptosis." (PMID 33374813, 2020). "HA was used as a targeting moiety against CD44-overexpressing breast cancer cells (MCF-7-ADR) and, thanks to its localized biodegradation by hyaluronidase concentrated at the tumor site, it also served for controlled and faster DOX release." (PMID 32373222, 2020).